RNU6-1116P (RNA, U6 small nuclear 1116, pseudogene)
Gene: Small nuclear RNA gene on chromosome 2 (37,435,510 to 37,435,608, reverse strand). Ensembl gene ENSG00000253078.
Homologues: Orthologues: chimpanzee U6 (100% identical), macaque U6 (97% identical). Paralogues in human: RNU6-454P (86% identical), RNU6-356P (85% identical), RNU6-560P (85% identical), RNU6-774P (85% identical), RNU6-824P (85% identical), RNU6-934P (85% identical), RNU6-1309P (84% identical), RNU6-249P (84% identical), RNU6-480P (84% identical), RNU6-80P (84% identical), RNU6-86P (84% identical), RNU6-87P (84% identical), and 1285 more.